PER3 (period circadian regulator 3)
Diseases named in the same sentence as PER3 in open-access papers (continued):
Sharing a sentence is not in itself a finding about the gene and the disease.
tumor (55 papers, 2010 to 2026). "Remarkably, tobacco smoke exposure of transgenic females caused repression of several tumor suppressors and included let-7f-5p while its circadian clock target gene Per3 was upregulated." (PMID 38245882, 2024). "The expression of PER3 is significantly downregulated in the tumor, which is associated with advanced tumor stages, tumor size, tumor invasion, and unfavorable patient survival." (PMID 34069297, 2021). "Altogether our data suggest that PER3 5/5 allele is preferentially selected during tumor development." (PMID 34508103, 2021). "Hypermethylation of the Per3 promoter was closely associated with tumor progression." (PMID 40041484, 2025). "Additionally, mutations of circadian genes are also present in SKCM; the most mutated genes are PER2 and PER3, which are classified as tumor suppressor genes." (PMID 37373286, 2023). "Furthermore, a bigger size of tumor was related with diminished PER3 and enhanced TIM expression, and increased tumor invasion was associated with decreased PER3 expression." (PMID 31151182, 2019). "Additionally, the PER3 gene is associated with the tumor infiltration status of multiple immune cell types and may play a role in the response of GBM patients to immunotherapy." (PMID 39771050, 2024). "Scheduled exercise at ZT2 significantly increased the amplitude of Per2, Per3, and Rev-Erbα expression rhythms in tumor tissue." (PMID 41736190, 2026). "Tumor growth, gene expression of Per1, Per2, Per3, and Rev-Erbα, and TNF-α concentrations were analyzed at six circadian time points." (PMID 41736190, 2026). "Enhanced expression of Per2 or Per3 inhibits tumor stem cell proliferation by suppressing Wnt signaling, while reduced PER3 levels stimulate Bmal1 expression and activate Wnt signaling." (PMID 40821111, 2025). "In tumor stem cells, increased expression of Per3 has been shown to inhibit both Notch and Wnt signaling, thereby reducing the self-renewal capacity of these cells." (PMID 40821111, 2025). "This indicates that the PER3 expression level can accurately differentiate the tumor tissue from the surrounding tissue adjacent to the tumor." (PMID 39771050, 2024). "The PER3 gene is expressed at low levels in tumor tissues of GBM patients and regulates GBM progression by modulating the expression of genes involved in the cell cycle and immune response." (PMID 39771050, 2024). "Our study demonstrated a potential relationship between aberrant expression of PER3 and tumor immune cell infiltration." (PMID 39771050, 2024). "PER2 and PER3 were also founded to be significantly up-regulated in the normal tissue compared to the tumor tissue." (PMID 37968308, 2023). "We observed allelic imbalance at the PER3 locus in matched blood and tumor DNA samples, showing a significant retention of the long variant (risk) allele in tumor samples, and a preferential loss of the short repetition allele (p = 0.0005)." (PMID 34508103, 2021). "In contrast, knockdown of PER3 in DN cells dramatically promoted their colony-forming and tumor-initiating capacities." (PMID 33816508, 2021). "In animal studies, PER3 OE dramatically inhibits tumor initiation of PC3 DP cells, whereas PER3 KD in PC3 DN cells notably promotes their tumorigenicity." (PMID 33816508, 2021). "Together, our results indicate that PER3 negatively regulates stemness of PCSCs via WNT/β-catenin signaling in the tumor microenvironment, providing a novel strategy to treat PCa patients." (PMID 33816508, 2021). "Taking the in vitro and in vivo results together, it was shown that Txnip, Aox1, Per3 and Ypel3 were consistently upregulated in both tumor lines and Acat2, Clspn and Ercc6l were downregulated." (PMID 33407762, 2021). "PER3 OE in PC3 DP cells decreased tumor initiating capacities as compared to controls (TIF 1/392 vs. 1/29, respectively, P = 0.00000315)." (PMID 33816508, 2021).
tumor (continued). "To determine the co-expression changes observed between PER3 healthy mammary tissues and the different tumor subtypes defined by the PAM50 algorithm we performed differential co-expression analysis in the human dataset (D1)." (PMID 34508103, 2021). "Analysis indicated that amongst nine studied clock genes, transcripts of PER3 highlighted a tumor size-dependent variation and an invasive depth-dependent variable pattern." (PMID 31151182, 2019). "Downregulation of PER3 and upregulation of TIMELESS (TIM) were characteristic for larger tumors, downregulation of PER3 for deeper tumor invasion and downregulation of PER1 and PER3 was associated with poor patient survival." (PMID 30760278, 2019). "PER1 and CRY1 were both up-regulated in neighbouring and tumour tissue compared to normal mucosa, while PER2 and PER3 were up-regulated in neighbouring mucosa and down-regulated in the tumour tissue." (PMID 27465361, 2016). "In particular, changes in the PER3 gene may directly accelerate tumor development by promoting the excessive proliferation of tumor cells and enhancing their anti-apoptotic ability." (PMID 40282437, 2025). "Among the stromal genes, we note that the everolimus+SNX631 combination upregulated an angiogenesis inhibitor Tnmd and putative tumor-suppressive proteins Acaca, Per3, and Ccl11, whereas Aldh1a2, a tumor stimulating stromal factor, was downregulated by the combination." (PMID 39541354, 2024). "Although the comprehensive mechanisms of the PRMT6/PARP1/CRL4B complex remain to be fully elucidated, our study reveals that the PRMT6/PARP1/CRL4B complex transcriptionally represses the core clock gene PER3, interrupting circadian clock oscillation, thereby promoting tumor progression." (PMID 36941223, 2023). "Therefore, the expression of Il6, Nos2, Ccl2, Spp1, Tnf, Acat2, Aox1, Crem, Gls2, Per3, Pink1, Txnip, and Ypel3 was examined in acidosis upon simultaneous transfection with microRNA mimics or antagomirs in two tumor lines in vitro and in vivo." (PMID 38069241, 2023). "This preferential retention could be due to the fact that changes in PER3 function derived from the presence of an additional VNTR repetition have a beneficial effect on tumor fitness." (PMID 34508103, 2021). "Moreover, the level of PER3 expression was negatively correlated with tumor stage and differentiation." (PMID 34721627, 2021). "PER3 overexpression in DP PCa cells significantly inhibits their clonogenicity and tumorigenicity, whereas PER3 knockdown in DN cells dramatically promotes their colony-forming and tumor-initiating abilities." (PMID 33816508, 2021). "This is consistent with the fact that PER3 protein is a tumor suppressor gene." (PMID 29570674, 2018). "PER1, PER2 and PER3 were lower in the tumour when compared to neighbouring benign mucosa." (PMID 27465361, 2016). "Previous studies have identified CHD5 and KIF1B as candidate tumor suppressor genes in this region, and more recently it was reported that disruption of PER3 function may indicate the likelihood of tumor recurrence in patients with ERα-positive tumors." (PMID 25106495, 2014). "Oshima's study has shown that the expression of Per3 in CRC tissues was significantly lower than that in the adjacent normal mucosa, suggesting that Per3 may function as a tumor suppressor gene." (PMID 21857934, 2011). "Moreover, PER3 overexpression in PCSCs was shown to significantly inhibit their clonogenicity and tumorigenicity, hence arresting tumor proliferation and development, while PER3 knockdown in non-PCSCs was shown to dramatically promote their colony-forming and tumor-initiating abilities." (PMID 36430659, 2022). "However, PER3 KD in PC3 DN cells promoted tumor formation (TIF 1/97 vs. 1/526, P = 0.000696)." (PMID 33816508, 2021). "Evidence suggests that PER3 may function as a tumor suppressor." (PMID 25501848, 2015). "The mechanism whereby PER3 may exert a tumor suppressor function is currently unknown." (PMID 25501848, 2015).
tumor (continued). "In the context of DNA damage, a tumor suppressive function has been suggested for the three PER genes (PER1, PER2, PER3)." (PMID 40352720, 2025). "The studies published so far showed both oncogenic and tumour suppressor functions of BMAL1, CLOCK, PER1, PER2, PER3, CRY2, and REV-ERBβ." (PMID 38378853, 2024). "Recent bioinformatics analyses have also shown that a variety of tumor markers are correlated with tumor immune infiltration in HNSCC, such as PER3, IDO1, MYL1 and HRPT1." (PMID 38937712, 2024). "Our study found significant differences in the expression level of PER3 in GBM tissues based on tumor histopathological staging, WHO grade, IDH type, tumor efficacy assessment, OS events, DSS events, and PFI events." (PMID 39771050, 2024). "Consistent with the nCV analysis, we found that rAMP decreased substantially in every core clock gene from normal to tumor, as evidenced by PER1 and PER3 expression." (PMID 37262074, 2023). "Protein expression analyses of the tumor relevant genes CREM GLS2, PER3 and TXNIP mostly showed a diametrical regulation compared to mRNA expression in both cell lines under acidotic conditions." (PMID 33407762, 2021). "The expression of CRY2, PER2, PER3 and RORA was correlated with TNM stage, T stage, and tumor differentiation in KIRC patients (p < 0.05)." (PMID 34977153, 2021). "Other noteworthy genes included DSPP, PER3, MTCH2, and KRT18, all have been reported with important roles in tumor formation and development." (PMID 32231683, 2020). "PER1, PER2, PER3, CRY2 were found to be significantly down-expressed, while CLOCK, TIMELESS were over-expressed in the studied tumor samples compared to the non-tumor samples." (PMID 29958276, 2018). "Among the clock genes, the expression of PER1, PER2, PER3 and CRY2 were significantly elevated in the benign tissue compared to the tumour tissue (p = 0.001, 0.002, 0.037 and 0.001 respectively)." (PMID 27465361, 2016). "Several clock genes showed a down-regulation when compared to their own neighbouring mucosa, i.e. PER1, PER2 and PER3, while CRY2 was down-regulated in both tumour and neighbouring tissue when compared to normal mucosa from unrelated donors." (PMID 27465361, 2016). "However, higher evidence for an oncogenic function was found for BMAL1 and CLOCK and higher evidence for a tumour suppressor function was found for PER2 and PER3, consistent with their role in the positive respectively negative arm of the clock network." (PMID 38378853, 2024). "However, PER2 and PER3 negatively correlate with tumor size, and TIM negatively correlates with tumor grade." (PMID 34697563, 2021). "Likewise, although NR1D2 and PER3 do not show significant differece between tumor and normal tissues, they do show significant correlation with survival conditions." (PMID 39043735, 2024). "Additionally, for the genes PRKAB1, PRKAB2, PER1, PER2, and PER3, methylation was observed in all samples, regardless of the tumor grade." (PMID 39001398, 2024).
psychiatric disorder (9 papers, 2013 to 2025). A disorder characterized by behavioral and/or psychological abnormalities, often accompanied by physical symptoms. "Strikingly, polymorphisms of Per3 were also shown to be correlated with mood health and psychiatric disorders." (PMID 39894345, 2025). "Particularly Per3 gene has been associated with chronotype, sleep homeostasis and various psychiatric disorders." (PMID 34273025, 2021). "A variable number tandem repeat (VNTR) polymorphism in Per3 has been associated with chronotype, sleep homeostasis and various psychiatric disorders." (PMID 34275002, 2021). "Taylor and Hasler also concluded that specific genes associated with chronotypes and psychiatric disorders include CLOCK, PER3, ARNTL, and TIM." (PMID 38124075, 2023).
infection (4 papers, 2015 to 2024). The state of being infected such as from the introduction of a foreign agent such as serum, vaccine, antigenic substance or organism. "Compared with the wild type, the mutants showed different parasitic abilities on the sclerotia of S. sclerotiorum after overexpression of Per3, and time after infection at which the fungal mycelia appeared on the sclerotia differed from 9 to 15 h." (PMID 25761240, 2015). "This module of 127 genes (including per3, csnk1d, ciart) was predominantly enriched for GO terms related to circadian functions (e.g. circadian regulation of gene expression), indicating significant disruption of molecular clock expression due to infection." (PMID 30285628, 2018). "Together, these results demonstrate that the sole presence of bacteria, in the absence of an infection, is sufficient to affect the expression of light-inducible (per2, cry1a) and non-inducible (per3, per1b) clock genes." (PMID 39537820, 2024). "Analyzing the pathogenesis-related genes in DEGs of all samples, the internal factor leading to the changes might be pathogen infection and seven genes (PRB1, PR-1, E137, PER3, PER47, STH-2, NLTP) which were clustered together could be important to it." (PMID 34221719, 2021).
metabolic disorder (2 papers, 2016 to 2020). "In our study, the expression of both per2 and per3 were decreased in the WD group, and the expression of Bmal1 was increased, which may lead to disruption of circadian clock and metabolic disorder, and the disturbed expression of per2, per3 and Bmal1 were all rescued by fish oil feeding." (PMID 26832365, 2016).
degenerative diseases (1 paper, 2021). "These include Spon2, Adam19, Arntl, Cdkn1a, Cry2, Per2, Per3, Wee1, Rcan1, Slc41a3, Errfi1, and Bhlhe41, which are related to numerous cardiovascular and degenerative diseases of other organs as well as varying aging processes." (PMID 33668521, 2021).
hematological disease (1 paper, 2021). "Genes highlighted here in, such as PRDM16, PER3, NOM1 BAHCC1, ZNF423, SETD7, RPTOR, and others have been implicated in hematological disease development, progression or clinical outcome." (PMID 34200630, 2021).
neurodevelopmental disorder (1 paper, 2019). A behavioral and cognitive disorder with onset during the developmental period that involves impaired or aberrant development of intellectual, motor, or social functions. "It remains to be elucidated if the ablation of neuronal network formation and/or maintenance really occurs in patients of neurodevelopmental disorders with PER3 mutation, and, if so, how the abnormality determines the clinical features." (PMID 30971765, 2019).
respiratory diseases (1 paper, 2023). "In fact, several genes are involved in respiratory diseases (BMALl1, FOXa2, CKIε, PER3, TIM, RORα, Clock, PER2-3, BHLHE40-41, REV-ERBα, and CRY1-2)." (PMID 38067152, 2023).
PER3 also shares sentences with these, for which no sentence is quoted: Glucose intolerance (3 papers); leukemia (3); Alzheimer disease (2); advanced sleep phase syndrome (1); astrocytic tumor (1); Atrophy (1); autoimmune disease (1); autoimmune thyroid disease (1); autosomal dominant tubulointerstitial kidney disease (1); bladder carcinoma (1); blood pressure (1); cardiovascular diseases (1); chronic kidney disease (1); Cognitive impairment (1); colorectal adenoma (1); colorectal tumors (1); dysfibrinogenemia (1); dysthymia (1); hemochromatosis (1); ichthyosis vulgaris (1); Infertility (1); liver fibrosis (1); lupus erythematosus (1); lymphedema (1); lymphoid leukemia (1); lymphoma (1); migraine (1); mucopolysaccharidosis type 2 (1); myalgic encephalomyelitis (1); non-Hodgkin lymphoma (1).
A further 12 diseases each share a sentence with PER3 in 1 paper.